ATF4 (activating transcription factor 4)
Diseases named in the same sentence as ATF4 in open-access papers (continued):
Sharing a sentence is not in itself a finding about the gene and the disease.
tumor (continued). "In vivo deletion of GCN2 in the myeloid compartment was associated with tumour growth restriction in different transplantable tumour models and with the phenotypic switch of TAMs and MDSCs towards a pro-inflammatory phenotype via the translational induction of ATF4." (PMID 34685679, 2021). "While we were able to find evidence of a defect in one-carbon availability in tumours from double-treated mice, we did not see a loss of an ATF-4 response." (PMID 33446657, 2021). "It remains possible that synthesis of other proteins may be retarded in double-treated mice, but the maintenance of the ATF-4 response likely reflects the retention of some serine availability to the tumour cell (potentially from surrounding stromal cells)." (PMID 33446657, 2021). "Tameire's study indicated that ATF4 plays an important role in MYC driven tumor progression." (PMID 33628101, 2021). "Recently, ATF4 has also been shown to be oncogenic; in Drosophila, activation of ATF4 induced a Warburg-like phenotype and consequently tumorigenic growth and in MYC-driven tumours, deletion of ATF4 prolonged survival, indicating that ATF4 is necessary for tumorigenesis." (PMID 33782711, 2021). "ATF4 is involved in regulating a variety of physiological and pathological processes, such as the regulation of hematopoiesis, osteoblast differentiation, endoplasmic reticulum stress, and tumor growth." (PMID 32656078, 2020). "Furthermore, CCT020312 inhibited tumor growth in an MDA-MB-453 orthotopic xenograft mouse model by activating the PERK/eIF2α/ATF4/CHOP pathway and inhibiting the AKT/mTOR pathway." (PMID 32508655, 2020). "IHC on tumor sections confirmed that paclitaxel increased ATF4 levels; this was reversed by ISRIB." (PMID 32427827, 2020). "Thus, CCT020312 inhibited tumor growth via the activation of the PERK/eIF2α/ATF4/CHOP signaling pathway and inactivation of the AKT/mTOR signaling pathway." (PMID 32508655, 2020). "The upregulation of ATF4-dependent expression of SLC1A5 and its splice variants eventually increase glutamine and tryptophan uptake that are highly demanded for rapid amino acids synthesis in tumor cells." (PMID 33330446, 2020). "However, it is well established that many stress‐responsive transcription factors, such as ATF4, exhibit protective or antitumor activity in normal cells but support tumor cell survival under severe stress conditions." (PMID 33108704, 2020). "Interestingly, such scenarios are also observed in several tumors, in which increasing evidence shows that the mammalian ortholog of Gcn4 (ATF4) is induced and assists in tumor proliferation." (PMID 33122193, 2020). "Moreover, within the tumour microenvironment, stromal fibroblasts can also upregulate ATF4 to induce metabolic changes that promote tumour proliferation." (PMID 32792521, 2020). "The new mechanistic connection between mitochondrial OXPHOS and ISR raises the possibility that altering nutrient and fuel availability to mitochondria could activate DELE1, HRI, and ATF4 to stop tumor growth." (PMID 33291682, 2020). "Reduction of ATF4 production should also result in attenuation of proapoptotic CHOP expression, which would not correlate with compromised growth of HepG2 cells and diminished tumor size caused by SERR induction." (PMID 32161259, 2020). "More generally, ATF4 plays an important role in many different tumor entities." (PMID 32938922, 2020). "The PERK/eIF2α/ATF4 pathway is key for maintaining ER homeostasis in the tumor microenvironment." (PMID 33003597, 2020). "However, most studies addressing the role of the PERK/eIF2/ATF4 signaling pathway in tumor cells focus on its role during UPR." (PMID 31395860, 2019). "Indeed, there is interest in targeting ATF4 for tumor therapy, as ATF4 is overexpressed in many cancers and appears to promote the survival of tumors." (PMID 30978945, 2019). "Therefore, further studies should illuminate the role of the PERK/eIF2/ATF4 signaling pathway in tumor progression." (PMID 31395860, 2019).
tumor (continued). "One of them, ATF4, promotes tumor cells proliferation via limiting oxidative DNA damage." (PMID 31491919, 2019). "In contrast, ATF4 activation has been shown to induce tumor cell death under stress conditions." (PMID 31461933, 2019). "Consistent with in vivo models, OS cells showed increased survival in response to BTZ when endogenous ATF4 was silenced; however, ATF4 overexpression alone not only suppressed the proliferation of tumor cells but also sensitized the cells to BTZ-induced growth arrest." (PMID 31534554, 2019). "ATF4 overexpression markedly decreased the tumor burden, which was comparable to the effect of BTZ." (PMID 31534554, 2019). "In relation to this, it was also shown that in non-small-cell lung cancer, oncogenic KRAS alters asparagine biosynthesis via the oxidative stress-responsive NRF2 and ATF4 transcription factors, to suppress apoptosis in response to glutamine deprivation and to sustain tumor growth." (PMID 31852884, 2019). "Since pharmacological activation of ATF4 exerts potent anti-tumor effects, modulators of ATF4 activation may have potential in cancer therapy." (PMID 31461933, 2019). "Moreover, continuous oral feeding with fucoidan significantly prevents tumorigenesis and reduces tumor size in addition to inducing ATF4 and CHOP protein expression in LLC1-bearing mice in vivo." (PMID 31041568, 2019). "Depletion of PKR in the mouse NEU tumor cells led to decreased eIF2α-P and ATF4 expression." (PMID 31086176, 2019). "This implies that in response to nutrient stress, oncogenic KRAS could likewise activate downstream NRF2 and ATF4-dependent antioxidant mechanisms to support tumor progression." (PMID 31852884, 2019). "This group of genes also includes 4E-BP1, leading the authors to hypothesize that, through ATF4-mediated gene induction, tumor cells couple enhanced translation rates with survival." (PMID 31998641, 2019). "As a key regulator of UPR8, the PERK/eIF2/ATF4 signaling pathway also regulates tumor progression." (PMID 31395860, 2019). "The significant correlations between the protein levels of IRF1 and eIF2α or ATF4 in the tumor tissues may result from high ER stress which trigger UPR in cancer." (PMID 30305853, 2018). "High TMB in the tumor tissue of lung SCC may activate the eIF2α/ATF4 pathway via neoantigen-induced UPR, which can induce NF-κB activation." (PMID 30305853, 2018). "It is worth noting that features of the solid tumor microenvironment such as hypoxia and nutrient deprivation have been associated with ATF4 overexpression regulated by the PERK/GCN2-eIF2α pathways and eIF2α phosphorylation has been shown to promote tumor growth." (PMID 29872155, 2018). "Pathway analysis revealed decreased expression of nine genes involved in cell proliferation and metabolism of tumor cell lines, indicating a role for upstream inhibition of the transcriptional regulator ATF4 and upstream activation of let-7 in our model of FBXO17 knockdown." (PMID 30359271, 2018). "Inhibition of glutamate release via ATF4 inhibition in fact disturbs tumor proliferation." (PMID 28881638, 2017). "Although the induction of CHOP after ER stress is primarily mediated through ATF4, it remains unknown the role of the CHOP-independent ATF4 effects in tumor-associated myeloid cells." (PMID 28105371, 2017). "Increased ATF4 expression was observed in murine and human tumor tissues." (PMID 28860159, 2017). "All together, these results confirm the hypothesis that a weak level of expression of ATF4 can contribute to the capacity of a subset of tumor cells to survive and proliferate in low concentration of amino acids." (PMID 28460466, 2017). "However, other studies have demonstrated that ATF4 is necessary for the survival of tumor cells in deprived environment." (PMID 28460466, 2017). "Previous studies have shown that ATF4 overexpression exists in many tumors, which suggests that it may play an important role in tumor formation, progression and metastasis." (PMID 29216929, 2017).
tumor (continued). "Moreover, increased expression of ATF4 has been reported to go along with the malignancy in human tumor pathologies." (PMID 28881638, 2017). "Furthermore, the ISR, which induces ATF4 expression, is also required for tumor survival and growth." (PMID 25941664, 2015). "ATF4 mRNA levels were the same in normal tissue and tumor tissue." (PMID 26123823, 2015). "Indeed, cells with compromised PERK-eIF2α-ATF4 signaling are more sensitive to hypoxic stress in vitro and they form slower growing tumors in vivo, indicating that the PERK-eIF2α-ATF4 pathway confers a survival advantage for tumor cells under hypoxia." (PMID 26258123, 2015). "Among all of the tumor samples that were analyzed, 30 (17.86%) demonstrated strong ATF4 staining (score of 9–12), 43 (25.60%) showed moderate staining (score of 5–8), 44 (26.19%) had weak staining (score of 2–4), and 51 (30.35%) exhibited negative staining (score of 0–1)." (PMID 25078779, 2014). "These phenotypic similarities may imply that TBL2 is involved in tumor cell adaptation to poor nutrient conditions through induction of ATF4." (PMID 25393282, 2014). "Emerging but limited evidence suggests that ATF4 regulates the metastasis of tumor cells." (PMID 25078779, 2014). "A recent study in mice revealed that inactivation of SKP2 induces tumour cell senescence that is dependent upon p27, p21 and the transcription factor ATF4, which is an integral component of the unfolded protein response (UPR) that is activated in response to endoplasmic reticulum stress." (PMID 21182779, 2010). "Together, this indicates that ATF4 could play a central role in the mechanisms of tumour growth regulation in general." (PMID 15846300, 2005). "Consistent with the previous verification, immunohistochemical staining of tumor tissues harvested from nude mice revealed that RPL41 treatment led to decreased expression levels of ATF4 and ARL5B in RB tissue, suggesting that RPL41 could inhibit the expression of these proteins." (PMID 41451209, 2025). "In addition to these classical immune modulatory roles, lncRNAs may also influence tumor–immune dynamics through ATF4 regulation." (PMID 40777108, 2025). "Cell death induced by both agents occurred due to prolonged ER stress, ATF4/CHOP pro-apoptotic function simultaneously with Rad51 downregulation and Ataxia Telangiectasia Mutated/Checkpoint kinase 2 (ATM/CHK2) activation, resulting in irreversible DNA damage and tumor doubling delay in vivo." (PMID 40563622, 2025). "Therefore, inhibition of ATF4 may be an effective target for reducing tumor growth by sensitizing cancer cells to ferroptotic cell death." (PMID 39021564, 2024). "However, ATF4 knockdown effectively inhibited tumor progression." (PMID 38994891, 2024). "Furthermore, IHC analysis revealed that COP diminished the expression of ATF4 and ASCT2 during glutamine restriction, thereby influencing the uptake and utilization of glutamine by ASCT2 within tumor tissues during glutamine deficiency." (PMID 38994891, 2024). "Notably, E16.5, the stage where the Atf4 null mouse lens becomes phenotypically abnormal, is approximately 800 microns in diameter, while the center of avascular tumor organoids that have reached this size is typically apoptotic/necrotic due to nutrient deprivation and tissue hypoxia." (PMID 37998373, 2023). "Similarly, ATF4 enhanced the tumor formation of GC cells in a xenograft model." (PMID 36900220, 2023). "Therefore, ATF4 may be an effective target for inhibiting tumor cell proliferation and tumor blood vessel growth." (PMID 35252001, 2022). "In addition, ATF4 is involved in regulating the biological behavior of tumor cells." (PMID 33628101, 2021).
tumor (continued). "Moreover, tumor cells may activate ATF4-mediated autophagy as a survival mechanism under stress conditions." (PMID 34834228, 2021). "However, in GC, ATF4 could significantly promote tumor progression and was negatively correlated with the prognosis." (PMID 34976799, 2021). "Moreover, ATF4 activity has been implicated in the chemo-resistance of CRC cells, further highlighting that NMD shut down by the tumor microenvironment can favor signaling cascades that potentiate tumor proliferation and malignancy." (PMID 33926465, 2021). "Finally, the ISR and ATF4 are mediators of tumor resistance to stress and therapy." (PMID 32938922, 2020). "We further examined whether ATF4 could induce tumor cell apoptosis." (PMID 31534554, 2019). "Furthermore, the ATF4/CHOP axis in tumor-infiltrating MDSCs accelerates apoptosis through death receptor 5 (DR5) and caspase-8 activation, suggesting that UPR activation plays a key role in modulating tumor-associated immune responses." (PMID 30282948, 2018). "Recent work on HT1080 and A549 tumor cells showed the phosphorylation of eIF2 by protein kinase RNA-like endoplasmic reticulum kinase increases the ability of these cells to cope with increased oxidative pressure in an ATF4-independent manner by activating Akt." (PMID 29312889, 2017). "Yet, increasing the level of expression of ATF4 might be an efficient strategy to target specific tumor cells able to resist to deprived environment, not only because ATF4 can be a pro-apoptotic factor but also, because low level of ATF4 might be the cause of the resistance." (PMID 28460466, 2017). "Thus, the capacity of a human tumor cell line to survive in low amino acid environment could be due to a decreased expression of ATF4." (PMID 28460466, 2017). "Thus, the upregulated expression of ATF4 is thought to facilitate tumor progression." (PMID 28881638, 2017). "Based on the fact that cytosolic HO-1 is able to translocate into the nuclei of certain tumor cells, it is possible that HO-1 could directly act as a transcription suppressor or indirectly regulate some transcription factors to inhibit ATF4 expression." (PMID 26925775, 2016). "Although several studies reported upregulation of ATF4 to be advantageous for tumor cells under unfavorable conditions, ATF4-mediated survival appears to be determined by both the level of ATF4 expression as well as the specificity of target genes activated by ATF4." (PMID 26657730, 2016). "Thus, we further investigated the infiltration of proangiogenic macrophages in tumor tissues and found that ATF4-overexpressing tumors could recruit more macrophages via secretion of macrophage colony stimulating factor (M-CSF)." (PMID 25883982, 2015). "However, it has not been discussed before whether exogenous overexpression of ATF4 in tumor cells can also influence tumor angiogenesis via regulating stromal cells in TME." (PMID 25883982, 2015). "However, ATF4 was inhibited in the tumor portion compared to the liver portion." (PMID 24198826, 2013). "Under endoplasmic reticulum stress, hypoxia, or nutrient deprivation, STC2 is upregulated and activates key survival regulators such as activating transcription factor 4 (ATF4) and HIF-1, thereby inhibiting apoptosis and enhancing tumor cell adaptation." (PMID 41596432, 2026). "Unsupervised analysis revealed a distinct tumor subset with low global protein synthesis but sustained translation of Integrated Stress Response (ISR) mRNAs, including ATF4." (PMID 41704035, 2026). "Mechanistically, aged tumour cells show increased sensitivity to the PERK-eIF2α arm of the unfolded protein response, sustaining persistent ATF4 signalling." (PMID 41813904, 2026). "Mechanistic investigations revealed pyrotinib promoted EGFR-GRP78 complex formation in the ER lumen, subsequently activating the PERK/ATF4/CHOP signaling pathway, and finally resulted in tumor apoptosis." (PMID 40830980, 2025).
tumor (continued). "As indicated by the immunohistochemistry (IHC) results, ATF4 or PFKFB3 knockdown decreased the staining intensity of Ki67, a proliferation marker of tumor cells." (PMID 40919132, 2025). "The ATP citrate lyase inhibitor BMS-303141 triggers the p-eIF2α/ATF4/CHOP axis, synergizing with sorafenib to suppress tumor growth, whereas 125I brachytherapy combined with lobaplatin amplifies apoptosis via the same pathway." (PMID 41407677, 2025). "In tumor cells, activation of key UPR molecules such as the IRE1α/XBP1 and PERK/ATF4 pathways promotes the formation of an immunosuppressive TME." (PMID 41407677, 2025). "Histone lactylation acidification participates in PERK-driven glucose metabolism and ATF4-regulated GLUT1 expression, regulates mononuclear cell-derived macrophage IL-10 expression, changes immunosuppressive activity, and promotes tumor progression." (PMID 41041328, 2025). "The histidine-rich calcium-binding protein enhances ERS adaptation through the PERK-eIF2α-ATF4-CHOP axis, fostering anoikis resistance and metastasis, with its expression correlating with tumor size and TNM stage." (PMID 41407677, 2025). "Elevated ROS levels in the tumor microenvironment increase exogenous cystine/cysteine uptake by activating transcription factor 4 (ATF4) to maintain elevated intracellular cysteine levels in CRC and support tumor growth." (PMID 40075600, 2025). "Further studies have identified molecules related to tumor MDR at the cellular level, such as downregulated miR-34a-5p and upregulated Activating Transcription Factor 4/(ATF4), both of which target SIRT1." (PMID 40567502, 2025). "For example, core ISR effector molecules like ATF4 and GCN2 can upregulate the expression of pro-survival genes, enabling tumor cells to survive under harsh conditions while potentially indirectly suppressing anti-tumor immune responses." (PMID 41409301, 2025). "Since IFNγ is one of the major immune stimulants that induce tumor cell stress, our results suggest that METTL5 continues to regulate ATF4 translation in OC cells even under the immune attack." (PMID 41042068, 2025). "Conversely, glutamine deprivation can induce ATF4 expression, forming a feedback loop that further enhances tumor adaptability to fluctuating nutrient conditions (Uncovering crosstalk between AMPK and the ATF4-Integrated Stress Response)." (PMID 40830338, 2025). "Tumor cells experience acute DNA damage, which leads to increased production of proteins such as cleaved PARP, ATF4, phosphorylated Chk1, and γ-H2AX." (PMID 41020897, 2025). "Our results align well with these studies, showing that the overexpression of ATF4 significantly boosts glycolysis in METTL1-knockdown cSCC cells, indicating a connection between m7G modification and tumor glycolysis." (PMID 39870616, 2025). "ATF4 or PFKFB3 knockdown significantly suppressed the xenograft tumor growth, as measured by the end point tumor weight." (PMID 40919132, 2025). "In response to therapeutic resistance mechanisms, tumor cells form adaptive escapes through ASNS and GAD metabolic branch activation, glucose/lipid metabolic compensation, and ATF4 transcriptional stress networks." (PMID 40598593, 2025). "Protodioscin also promoted the binding of ATF4 to the CHOP promoter, thus contributing to tumor apoptosis." (PMID 40002335, 2025). "MAPK inhibition attenuates the translational induction of ATF4 and its target ASNS, sensitizing pancreatic tumors to asparagine restriction and thus inhibiting tumor growth." (PMID 39796613, 2025). "Specifically, butyrate depletion in tumor-adjacent niches leads to HDAC-mediated hyperacetylation of the PDCD1 promoter, which is then recognized and bound by ELF3 and ATF4." (PMID 41438381, 2025). "Intriguingly, ATF4 directly binds the VEGFA promoter to enhance transcription during ER stress, a pathway co-opted in tumor angiogenesis." (PMID 41010531, 2025).